MCL1 (MCL1 apoptosis regulator, BCL2 family member)
Diseases named in the same sentence as MCL1 in open-access papers (continued):
Sharing a sentence is not in itself a finding about the gene and the disease.
cancer (continued). "Similar to 2D results, despite a difference in the treatment concentration, cleaved caspase 8 and PARP expression markedly increased, whereas Mcl‐1 expression decreased upon PYR administration, indicating that PYR may induce Mcl‐1‐mediated and caspase‐dependent apoptosis in cancer cell spheroids." (PMID 40765495, 2025). "For example, K604-Gln-intact cancers could be sensitized to HU and ALS treatments through the Gln-K604 inhibitor glutaminol, whereas Gln-K604-null cancers could be sensitized by silencing c-MYC and MCL-1." (PMID 40338031, 2025). "BCL2L1 methylation is a predictor of MCL1 inhibitor response in CNS and non-CNS pediatric cancers." (PMID 39846250, 2025). "However, the exact role of Mcl-1 in IMQ-induced apoptosis, including its protective mechanisms and physiological function in cancer cells, remains unclear." (PMID 39272918, 2024). "Thus, it can be reasonably expected that a clinical-grade DHODH inhibitor combined with venetoclax might improve outcomes for HGBCL patients, as well as other cancers with high expression of MYC and BCL2 or MYC and MCL-1." (PMID 38918775, 2024). "However, the role of Mcl-1 in IMQ-induced cell death, as well as its protection-conferring mechanism and physiological function in cancer cells, remains unclear." (PMID 39272918, 2024). "However, it has been reported that the overexpression of Bcl-2 and Mcl-1 in various hematologic cancers, including NHL, may lead to dysregulation of the apoptosis rate, benefiting cancer progression." (PMID 38731446, 2024). "However, the level of MCL1 expression itself does not correlate with MCL1 inhibitor response in cancer cells." (PMID 39802137, 2024). "This regulation of MCL1 by MARCH5 could be exploited in other cancer scenarios, where MARCH5 has not yet been investigated and where the ligase may have a tumor suppressor role, despite opposite results in other cancers." (PMID 38139010, 2023). "Activation of ISR by a combined treatment of cancer cells with Navitoclax, that acts through B cell lymphoma extra-large (BCLXL) blockade, and protein kinase inhibitors induces MARCH5-mediated ubiquitination and proteolysis of the BCL2 family apoptosis regulator (MCL1)." (PMID 36672167, 2023). "However, many cancers depend on different pro-survival proteins for sustained growth (e.g. MCL-1) and so do not respond to Venetoclax." (PMID 37567974, 2023). "In the absence of FBW7, MCL-1 protein accumulates, and cancer cells escape Taxol induced death." (PMID 36672454, 2023). "Besides, by inhibiting the expression of MCL-1, an anti-apoptotic protein, and VDAC1/2 that is essential for the release of cytochrome C from mitochondria to the cytoplasm, miR-29a promoted apoptosis in cancer cells." (PMID 36140219, 2022). "Furthermore, some tumors overexpress specific cancer genes located on 1q (e.g., MDM4, ABL1, MCL1) indicating that these patients might benefit from targeted therapies in the future." (PMID 36230794, 2022). "The effects of MCL1 and B3GNT2 overexpression could be generalized to six and seven of the additional cell lines respectively, demonstrating the broad applicability of these candidate genes to other cancer types and supporting the patient tumor analyses." (PMID 35338135, 2022). "However, neither the silencing of MCL-1 in CAFs nor its inhibition by S63845 detectably increased cancer cell migration or proliferation, as evaluated by wound-healing assays and time-lapse video-microscopy." (PMID 36104324, 2022).
cancer (continued). "Thus, cancer cells may acquire chemotherapy resistance via different mechanisms and our findings suggest TRIP12 as a potential target to tackle MCL1-driven chemotherapy resistance." (PMID 33824312, 2021). "Consistent with the notion that evasion of cell death is a hallmark of cancer, the pro-survival proteins BCL-XL and MCL-1 were found in amplification peaks when compared to non-cancerous samples, whilst pro-apoptotic proteins such as BOK and PUMA were identified in deletion peaks." (PMID 33799592, 2021). "Moreover, SRSF1 also regulates the splicing of some other cancer-related genes, such as BIM, BIN, and MCL1, which might account for that ectopic expression of Bcl-xL only partially rescues the phenotype." (PMID 33664238, 2021). "Taken together, the results of this study showed that the reductions of anti-apoptotic proteins and alterations to MCL1 splicing is an important mechanism of CLK-induced cell death and the use of CLK inhibitors in combination with Bcl-xL/Bcl-2 inhibitors presents an option for cancer therapy." (PMID 33064779, 2020). "In agreement with the use of Mcl-1 as a target for cancer therapy, our previous study highly supported this concept, where in our experiments, the treatment of RT in an NSCLC cell line (H460) resulted in apoptotic cell death through an Mcl-1 proteasomal degraded mechanism." (PMID 32260280, 2020). "This may reflect a higher dependency on MCL1 and MYC, or apoptotic priming, in cancer cell lines." (PMID 32645016, 2020). "In contrast to other Bcl-2 family members, MCL-1 is usually not involved in translocations; also mutations of MCL-1 are very infrequent (detected in approximately 1% of all cancers) although they were shown to prolong MCL-1 stability and affect the activity of MCL-1 inhibitors." (PMID 33308268, 2020). "For example, the downregulation of BCL-2 reflects the loss of addiction to this protein, but the compensatory upregulation of the anti-apoptotic proteins not targeted by venetoclax (BCL-XL and MCL1) is observed in leukemia or cancer cell line venetoclax-treated cells." (PMID 31226848, 2019). "MCL1 was expected to be a negative prognostic factor in many cancers." (PMID 31467488, 2019). "Although BH3-only proteins were required for apoptosis induced as a result of BCL-XL inhibition, this requirement was overcome when both BCL-XL and MCL-1 were inhibited, implicating distinct mechanisms by which different anti-apoptotic BCL-2 family members may regulate apoptosis in cancer." (PMID 30185825, 2019). "However, some carcinomas remain resistant to TRAIL-mediated cell death by regulating apoptosis-related proteins, such as death receptors (DR4 and DR5) and anti-apoptotic proteins (IAPs, FLIP, and Mcl-1)." (PMID 31075907, 2019). "Mcl-1 has attracted attention because of its established role in preventing cell death by binding and sequestering pro-apoptotic BH3 proteins, thereby mediating cancer cell survival, as well as intrinsic and acquired resistance against cytotoxic and some targeted therapies, including venetoclax." (PMID 30559424, 2018). "Therefore, we propose that deubiquitinase USP13 is a new regulator of MCL1 stability and drug sensitivity to BH3 mimetic inhibitors, and may represent a promising therapeutic target for cancer treatment." (PMID 29335437, 2018).
cancer (continued). "However, many Mcl-1 inhibitors obtained from prior efforts are potent to activate the mitochondrial apoptotic pathway by upregulating PUMA, leading to apoptosis in both cancer and normal cells." (PMID 28903337, 2017). "Subsequently it was demonstrated that pyridoclax sensitises various cancer cells (IGROV1, OAW42‐R, SLOV3, A549 and MSTO‐211 H) to Bcl‐xL knock‐down, and chemoresistant ovarian cancer cells to ABT‐737 (IGROV1‐R10 and SKOV3) at 25 μm, suggesting Mcl‐1 selectivity." (PMID 26696548, 2016). "Indeed we found that SDE-genes identified in previous step are related to STAT3 pathways including genes involved in cell cycle progression (Cyclin D1, D2, and c-Myc), cell survival (Bcl-xL, Bcl-2, Mcl-1), angiogenesis (HIF1α, VEGF), cancer inflammation (NF-KB, IL-6)." (PMID 26056083, 2015). "Regardless of Mcl-1-dependency specific knock-down of Bag3 sensitizes cancer cells to the cytotoxic effects of ABT263 and ABT737, suggesting that interference with Bag3 may be useful to chemo-sensitization." (PMID 26474387, 2015). "TRAF6 and MCL-1 may therefore represent viable therapeutic targets for ATL and other cancers." (PMID 25340740, 2014). "Overall, Thr163 phosphorylation can prime GSK3-targeted Mcl-1 degradation to promote death in normal cells, whereas in cancer cells in which degradation is not dependent on this pathway, ERK-mediated phosphorylation of Thr163 is associated with Mcl-1 stabilization and drug resistance." (PMID 24814761, 2014). "Interestingly, both Mcl-1 and survivin share transcriptional regulation by SP1, providing an additional molecular basis for the dual suppression of these critical pro-survival factors in cancer cells." (PMID 25296978, 2014). "Therefore, it is not surprising that Mcl-1 protein level is strictly controlled in normal cells, and that cancer cells have a vast arsenal to ensure high levels of Mcl-1 and thereby escape apoptosis." (PMID 24814761, 2014). "Therefore, TRAF6-mediated MCL-1 stabilization appears to be a common mechanism of cell survival usurped by both viral and non-viral cancers." (PMID 25340740, 2014). "Indeed, studies showing a stabilization effect have been performed in various cancer cell lines in which Mcl-1 degradation was found to be independent of the GSK3 pathway." (PMID 24814761, 2014). "ABT-737, the most well-known member of a class of Bcl-2-family targeting compounds, and its orally active analog ABT-263, have activity as single agents in a subset of cancers (including multiple myeloma and small-cell lung cancer) that rely on Bcl-2/Bcl-xL, but not Mcl-1, for survival." (PMID 23680104, 2013). "Furthermore, regarding the effects of Mcl-1 on invasion, there is no supportive experimental data available on any cancer entity so far." (PMID 24098503, 2013). "The first group consists of cancer cells whose drug resistance can be overcome by exposing the cells to GCs in combination with drugs that target protein kinases such as Akt, mTOR, Src, ALK, and/or BCR, or drugs antagonizing Bcl-2, Bcl-XL, Mcl-1, c-Myc, or Notch." (PMID 23431463, 2013). "In these cancer cells in which Mcl-1 degradation is not dependent on the GSK3/phosphodegron-targeted pathway, ERK activation and Thr 163 phosphorylation are associated with pronounced Mcl-1 stabilization and drug resistance – effects that can be suppressed by inhibition of ERK activation." (PMID 23056582, 2012). "Because several studies in various cancer types have demonstrated that overexpression of the antiapoptotic protein Mcl-1 may promote TRAIL resistance, we examined the contribution of Mcl-1 to ascites-induced TRAIL resistance in the TRAIL-sensitive OC cell line CaOV3 and OVCAR3." (PMID 23158473, 2012).
cancer (continued). "Based on these findings, we speculated that those ER stress-activating agents may increase the expression of Noxa, leading to the reduction or inhibition of Mcl-1; and this characteristic may merit them as potential combination candidates with ABT-737 by exerting synergistic anti-cancer activities." (PMID 23284992, 2012). "How 2DG treatment of cancer cells disrupts Bak-Mcl-1 is not known." (PMID 21949692, 2011). "Mcl-1 immunointensity was increased from normal tissues to well-differentiated cancer and further elevated in high grade PCa, although the difference between Mcl-1 intensity in intermediate- and poorly-differentiated cancers was not statistically significant (p = 0.93)." (PMID 20085644, 2010). "For instance, research reveals that the degradation of anti-apoptotic Mcl-1, mediated by Noxa during prolonged mitotic arrest (M-arrest), involves mitochondrial E3-ligase MARCH5, suggesting that inhibiting MARCH5 could enhance MTAs in cancers like HeLa and A549." (PMID 40841912, 2025). "Additionally, TRIP12/MCL-1 expression might be a useful biomarker for texane-based chemotherapy response in some but not all cancers." (PMID 36672454, 2023). "Furthermore, we speculate that the reason for AZ PFKFB 67 does not induce cell death by itself, even in MCL-1-addicted cancer cells, is that the remaining MCL-1-protein levels following AZ PFKFB3 treatment may be sufficient to sustain cell survival." (PMID 37684238, 2023). "Besides, USP13 depletion dramatically inhibited cancer cell proliferation and suppressed tumor growth in xenograft models while reintroduction of MCL-1 partly restored cell proliferation and increased the tumor volume, reinforcing the regulation of MCL-1 by USP13." (PMID 36188217, 2022). "Moreover, vandetanib treatment could decrease the protein expression of MCL‐1 and BCL‐2 and increase the expression of BAD, BAX and BAK in K562 tumor tissues, which was consistent with the regulation of apoptosis‐related proteins in cancer cells in vitro." (PMID 35689424, 2022). "Therefore, silencing MCL1 by GA-T0 also could target CREB protein, a downstream transcription factors of the PI3K/Akt signaling pathway, which is highly regulated in most cancers." (PMID 34359676, 2021). "Importantly, numerous non-apoptotic roles for MCL-1 have also been described that may also be relevant to cancer." (PMID 33785871, 2021). "Moreover, Mcl-1 is the target protein of the TRAIL signaling pathway, and the activation of TRAIL can downregulate the expression of Mcl-1 at the transcriptional and post-transcriptional levels, further indicating that Mcl-1 can be used as a target of cancer drugs." (PMID 33322296, 2020). "However, as cancer cells may be dependent on other anti-apoptotic proteins due to their heterogeneity and phenotype/genotype plasticity, BH3-mimetics targeting the other prosurvival proteins BCL-xL or MCL-1 are also undergoing clinical investigation." (PMID 32722518, 2020). "Finally, through gene expression analysis, we identified signaling molecules that might contribute toward TRAIL and MSC-TRAIL resistance in CD133+ CSCs, and uncovered NFKB1, BAG3, MCL1, GADD45A, and HRK as potential anti-cancer genes that could increase sensitivity of NSCLC to MSC-TRAIL therapy." (PMID 31466290, 2019). "Although CDK9 inhibition suppresses MCL1 expression, it does not affect levels of other anti-apoptotic proteins such as Bcl-xL, exposing a potential vulnerability in CDK9i treatment such that cancers may already have or develop a mode of resistance." (PMID 31294695, 2019).
cancer (continued). "Besides MCL-1-mediated resistance, modulation of ncRNAs controlling the BCL-2 family, alone or in combination with other agents, could be explored as a therapeutic strategy against cancer." (PMID 29570632, 2018). "Mcl-1 expression, however, does not seem to be the unique factor determining the susceptibility towards CG treatment as the comparison between basal levels of the major anti-apoptotic Bcl-2 family proteins and susceptibility to UNBS1450 in the panel of cancer cell lines examined is suggesting." (PMID 26068790, 2015). "Indeed, phosphorylation-defective mutations of these different serine and threonine residues stabilized Mcl-1 and increased protection from apoptosis following growth factor withdrawal, expression of constitutively active GSK3, UV irradiation and anti-cancer drugs." (PMID 24814761, 2014). "Thus, TRAF6 regulates the basal stability of MCL-1 in some, but not all cancer cell lines." (PMID 25340740, 2014). "Given that few or no specific inhibitors of Mcl-1 are currently available, the use of citrate targeting Mcl-1 could be of major interest for it could contribute towards the destruction of chemoresistant cancer cells." (PMID 24103422, 2013). "Consequently, owing to the Noxa-regulating effect of Celastrol, and the Mcl-1-resistant feature of ABT-737, we proposed that the combination of Celastrol with ABT-737 may achieved synergistic anti-cancer activity, and several experiments were performed to prove our hypothesis." (PMID 23284992, 2012). "Although FAO modulates neurodevelopment and MCL-1 is known to play a role in cancer cell FAO, the role of MCL-1 in FAO during human neurodevelopment has not been explored." (PMID 41427398, 2025). "Significant tumor regression arising from synergistic inhibition of BCL‐XL and MCL1 has not yet been reported for HGSOC, but is known to induce solid tumor regression in other cancers." (PMID 36925689, 2023). "A model has been proposed that SF3B-targeting splicing modulators preferentially perturb RNA splicing of MCL1 and BCL2A1, but not of BCL2L1 (BCLxL), leading to selective cytotoxicity in MCL1- or BCL2A1-dependent cancer cells." (PMID 37562845, 2023). "The feasibility of re-purposing specific MCL-1 and BCL-2 inhibitors to limit M.tb growth, using inhibitors that are in clinical trials and FDA-approved for cancer treatment has not be tested previously." (PMID 37864894, 2023). "Although there are some reports that the DNA methylation signature regulates apoptosis in cancer cells, no studies have shown a link between apoptosis-related genes such as BCL-2 or MCL-1, and DNA methylation." (PMID 35185150, 2022). "Our study suggests that lucanthone, an autophagy inhibitor, sensitizes TRAIL-induced apoptosis via Mcl-1 downregulation and DR5 upregulation in cancer cells, but not normal cells." (PMID 35008442, 2021). "These proteins, which include BCL-2, BCL-XL, MCL-1, BCL-W and BFL-1, are key negative regulators of the intrinsic apoptosis pathway which is deregulated in most, if not all cancers." (PMID 34581776, 2021). "There are to date no selective inhibitors for BCL-W, which can render cancer cells nonresponsive to BCL-XL and MCL-1 inhibition." (PMID 32312973, 2020). "The HHT mode of action in this cancer has not been precisely demonstrated although HHT decreased the cellular levels of MYC, MCL-1, SURVIVIN and also interfered with JAK1 and STAT3 phosphorylation, to decrease the levels of IL6, a growth factor for NSCLC." (PMID 32151059, 2020). "Unlike several hematological malignancies, cancer cells derived from most solid tumors depend on both BCL-XL and MCL-1 for survival." (PMID 30185825, 2019).